S100A12 (S100 calcium binding protein A12)
Diseases named in the same sentence as S100A12 in open-access papers (continued):
Sharing a sentence is not in itself a finding about the gene and the disease.
tumor (continued). "Western blot assays confirmed that the protein levels of S100A12 were decreased in tumor cells from the shRNA#1 group compared with tumor cells from the shNC group." (PMID 32015423, 2020). "For UCB our data showed that expression of S100A12 found at the highest level in normal bladder tissue adjacent to the tumor and at much lower levels in tumor itself and normal tissue." (PMID 31993369, 2019). "It has been reported that the abnormal expression of S100A12 is closely related with inflammation and vascular invasion of tumor cell, over inflammation and vascular invasion are closely related with tumor recurrence/metastasis." (PMID 24839399, 2014). "The S100A12 is markedly overexpressed at sites of inflammation, and elevated serum S100A12 levels were detected in individuals with inflammatory, neurodegenerative, metabolic, and neoplastic diseases." (PMID 40072746, 2025). "Higher concentrations of the S100/calgranulins were detected in dogs with inflammatory or neoplastic urinary tract diseases than in healthy dogs, and the S100A8/A9-to-S100A12 ratio was significantly lower in dogs with inflammatory conditions compared to those with neoplastic disease or health." (PMID 36411489, 2022). "Moreover, S100A12 expression was related to pathological features, including the tumor grade and stage and lymph node metastasis status." (PMID 32015423, 2020). "These in vitro results demonstrated that silencing S100A12 reduced the progression of tumor cells." (PMID 32015423, 2020). "Further research is also needed to determine when changes in S100A8/A9 and S100A12 could possibly occur along the spectrum of tumor development and whether these tests can detect pre-cancerous pathology or early cancer." (PMID 28431528, 2017). "We identified six cell types, including macrophages (PPP1R17), monocytes and neutrophils (FCAR, S100A12, CD93), tumor stem cells (CPZ), smooth muscle cell populations and epithelial cells (CSF3, TTC23L)." (PMID 41049004, 2025). "The results showed that the expression levels of CTHRC1, APOD, and S100A12 in the tumor group were significantly upregulated, whereas the expression levels of ASCL2 in the tumor group were significantly downregulated." (PMID 40898459, 2025). "In the tumor array, correlations were observed between S100A9 and S100A8 (R = 0.62), S100A4 (R = 0.78), S100A10 (R = 0.51), S100A12 (R = 0.76), and HMGB1 (R = 0.80)." (PMID 37627239, 2023). "In contrast to the presumed specificity of S100B, a variety of tumours and cells originating from all germ layers can be induced to express S100 proteins, particularly S100A8, S100A9, S100A12 and S100B, as a result of oxidative stress and tissue inflammation." (PMID 35323240, 2022). "As a result, we found that CD163, CD74, S100A4, S100A12, HLA-DRA, and HLA-DRB1, which are usually highly expressed in myeloid cell, were also highly expressed in tumor cells of cluster 6; thus, we termed this cluster myeloid-like tumor cells." (PMID 37138326, 2023). "Interestingly, in the blood, patients with high-expression S100A12 were more likely to have lower scores of B cells, CD8 T cells, Th1 cells, Th2 cells, tumor infiltrates lymphocytes (TIL), and check point." (PMID 35185901, 2022). "Comparing noncancerous gastric mucosa and tumor tissue, S100A12 was expressed in gastric epithelial cell lines and stromal cells (i.e., monocytes, lymphocytes, and neutrophils) in both conditions." (PMID 32184815, 2020). "The authors detected a negative correlation between S100A12 expression in tumor cells and GC markers of severity, such as size, depth of invasion, TNM stage, Lauren classification, and tumor cell differentiation." (PMID 32184815, 2020). "S100A12 appears to be mostly expressed in cells contained within the stroma and not in the tumor tissue." (PMID 31993369, 2019).
tumor (continued). "Interestingly, 4 of the top 5 up-regulated proteins in tumor TIF were all S100 family members, including S100P (ratio = 40.9), S100A9 (ratio = 19.0), S100A8 (ratio = 5.3) and S100A12 (ratio = 4.5)." (PMID 27216119, 2016).
cancer (29 papers, 2009 to 2025). A tumor composed of atypical neoplastic, often pleomorphic cells that invade other tissues. "Human S100A12 is a member of the S100 family of EF-hand calcium-modulated proteins that are associated with many diseases including cancer, chronic inflammation and neurological disorders." (PMID 19386136, 2009). "While functions and interactions of individual DAMPs have not been comprehensively characterized, in general HMGB1 and HSP70 reflect the degree of surgical injury or tissue damage, while increased S100A8/9 and S100A12 are associated with morbidity and mortality and cancer progression." (PMID 38468349, 2024). "We found that the expression of S100A12 was significantly associated with aggressive cancer." (PMID 38719807, 2024). "The higher transcript levels of S100A12 observed in HPNE cells than in the cancer cells could also be indirectly caused by changes in the senescence abilities of these cells." (PMID 37627239, 2023). "In our study, S100A12 was strongly associated with DFS and DDFS endpoints, had higher serum levels in cancer compared to benign samples, and was also part of the 17-protein signature." (PMID 38594742, 2024). "It was worth noting that the expression levels of CXCR4, PPP3R1, HSP90AB1, CXCL10, and S100A12 were substantially elevated in multiple types of cancer tissues." (PMID 36569892, 2022). "In line with S100A9 and S100A12, high blood monocyte count was shown to be associated with shorter PFS and cancer-specific survival in patients with metastases." (PMID 34067757, 2021). "In particular, S100A8, S100A9 and S100A12 are highly abundant proteins released by neutrophils and have been identified as important biomarkers in many inflammatory diseases and cancers." (PMID 33468080, 2021). "Multiple studies have reported that S100A12 is involved in cancer-related processes and positively correlated with the prognosis of cancer." (PMID 32015423, 2020). "One gene group that has been shown to have these properties recently is the S100 protein family and S100A12 in particular, which is expressed in different type of cancers." (PMID 31993369, 2019). "The ROC analysis study showed that the ideal cancer-vs.-control plasma concentration threshold of S100A12 was 350 ng/mL to maximize the test's sensitivity and specificity." (PMID 31993369, 2019). "Currently, research on the correlation between S100A12 and cancer are limited." (PMID 40072746, 2025). "Notably, we detected several critical regulating proteins associated with cancer processes, such as CAMP, MMP9, the S100 family (100A8, S100A9, S100A12), and PRTN3, among the proteins with the most significant increases." (PMID 37231509, 2023). "A trend for reduced cancer-specific survival was also seen in patients of S100A12." (PMID 34067757, 2021). "First, S100A12 could act from inside cancer cells to activate ERK1/2 pathways." (PMID 32015423, 2020). "Taken together, LTF, ARG1, PGLYRP1, S100A12 and CAMP/LL-37 affect the human immune system at various levels by producing both protumorigenic and anticancer effects in a tissue- and cancer-specific manner." (PMID 36230605, 2022). "Based on the Oncomine database, there are no obvious distinctions in S100A1, S100A4, S100A5, S100A6, and S100A13 expressions between cancer tissues and normal colon mucosa, and S100A7, S100A12, and S100Z are slightly overexpressed in CRC tissues." (PMID 33294444, 2020). "We conclude that S100A12 is an independent and significant prognostic marker for UCB patients, which may predict the disease course of UCB patients and facilitate the clinical management of this cancer." (PMID 31993369, 2019). "However, S100A12 has not been investigated extensively in cancer patients." (PMID 28431528, 2017).
cancer (continued). "For cancer vs. non-cancer prediction, the top-performing model included the plasma concentrations of ARG1, CA2, F13A1, and S100A12, achieving an mAUROC of 85.3% (72.8–97.8% (95% CI))." (PMID 41155404, 2025). "Although for most S100s, and for HMGB1, the transcript levels were lower in the control HPNE cells than in the cancer cell lines, this was not the case for S100A4, S100A6, S100A7, S100A12, and S100A13." (PMID 37627239, 2023).
cardiovascular disease (16 papers, 2010 to 2025). "Among the S100 family of binding proteins S100A8, S100A9, and S100A12 have been identified as DAMPs and linked with cardiovascular disease (CVD)." (PMID 38275751, 2023). "S100A12 decreased after 52 weeks of a rigorous cardiovascular disease risk reduction program with comprehensive lifestyle changes." (PMID 35795659, 2022). "In a previous cross-sectional study, plasma S100A12 levels were measured in 550 maintenance hemodialysis patients to determine the association between S100A12 and the prevalence of cardiovascular diseases (CVD)." (PMID 23324110, 2013). "Reports have highlighted the significance of serum S100A12 levels in diagnosing, predicting, and prognosticating cardiovascular diseases, positioning it as a novel biomarker for forecasting cardiovascular events." (PMID 39444551, 2024). "A cross-sectional study of 550 hemodialysis patients showed that S100A12 protein levels were closely related to the prevalence of cardiovascular disease." (PMID 33388092, 2021). "S100A12 may have a role as a biomarker of future cardiovascular disease, and may be able to be incorporated into primary prevention and risk factor modification." (PMID 30467547, 2018). "Among these mechanisms, stimulation of the advanced glycation end product (AGE) receptor by a low-molecular weight AGEs like pentosidine or by compounds of the S100/calgranulin family like S100A12/ENRAGE is a relevant pathway leading to cardiovascular disease and renal damage in CKD patients." (PMID 29362665, 2017). "Our results are in line with previous evidence of elevated expression of S100A12 in coronary arteries from diabetic patients (compared to non-diabetic), and that elevated plasma S100A12 has been associated with prevalence of cardiovascular disease and PAD in cross-sectional studies." (PMID 26216409, 2015). "The effect was decreased after adjustment for Framingham cardiovascular disease score: risk for amputation or death, HR 1.17; 95% CI [0.94, 1.46] and 1.54; [0.95, 2.49], and risk for PAD or death, HR 1.12; 95% CI [0.91, 1.38] and 1.38; [0.91, 2.11] for S100A12 and RAGE-score respectively." (PMID 26216409, 2015). "Previous studies have shown that S100 protein family members are involved in cardiovascular disease, such as S100B, S100A8, S100A9, and S100A12." (PMID 31275446, 2019).
bacterial infection (12 papers, 2008 to 2024). "The higher plasma levels observed in turtles with traumatic injury are consistent with the association of S100-A12 with trauma and possibly secondary bacterial infection of the wounds." (PMID 33959286, 2021). "BacSig was defined as the signature of the host response to bacterial infection using the average expression of five representative genes, including S100A12, CD177, HP, ANXA3, and ARG1." (PMID 38790931, 2024). "In previous works, we have proposed S100A12 as the most prominent host marker for bacterial infection which was compared favorably against PCT and CRP in over a thousand clinical samples." (PMID 36649304, 2023). "The reason for the selection of S100A12 expression in this study is that it stands out to be the most prominent marker for bacterial infection in our previous works." (PMID 34108608, 2021). "Since most genes including immune-related genes are multi-functional, it is conceivable that the function of S100A12 is not limited to the response to bacterial infection." (PMID 34108608, 2021). "All of the samples in this group had higher S100A12 expression than the highest value in the control groups, again validating S100A12 expression as a prominent marker for bacterial infection." (PMID 34108608, 2021). "Human hosts respond to viral and bacterial infections in different ways, the former is characterized by the activation of interferon stimulated genes (ISGs) such as IFI27, while the latter is characterized by the activation of anti-bacterial associated genes (ABGs) such as S100A12." (PMID 36649304, 2023). "S100A12 and CD177 gene-expression analysis in blood effectively diagnosed bacterial infections with high sensitivity and specificity." (PMID 39066246, 2024). "This is because S100A12 activation is the most prominent signature of bacterial infection (with or without viral co-infection)." (PMID 36649304, 2023). "S100A12 and PTX3 mRNAs were markedly up-regulated in bMEC stimulated with LPS and LTA indicating that they may be involved in the initial response of mammary tissue to bacterial infection." (PMID 18513449, 2008).
infectious disease (9 papers, 2013 to 2026). A disorder directly resulting from the presence and activity of a microbial, viral, or parasitic agent in humans. "At present, S100A8, S100A9, and S100A12 proteins generated from human or mouse sources have been extensively studied and proven to be powerful in the prevention and treatment of infectious diseases." (PMID 38256103, 2024). "S100A8, S100A9, and S100A12 proteins are important members of the S100 protein family, act primarily as congenital immunomodulators, and are closely related to the occurrence of infectious diseases." (PMID 38256103, 2024). "Serum S100A12 is a marker of inflammatory disease as well as infectious disease." (PMID 30366444, 2018). "There is limited information on the role of S100A12 in infectious disease, leading us to test the hypothesis that S100A12 contributes to host defense against mycobacterial infection in humans." (PMID 27355424, 2016). "And serum levels of S100A8/9 and S100A12 are also elevated in SLE and infectious disease." (PMID 30687316, 2018). "One of these, S100A12, is present in humans, but not mice, has limited studies in infectious disease." (PMID 27355424, 2016). "Nevertheless, little is known about the role of S100A12 in infectious disease, since the gene is present in humans but not mice." (PMID 27355424, 2016). "Given that S100A12 is present in humans and not mice, little is known about its role in human infectious disease, leading us to hypothesize that S100A12 contributes to host defense against mycobacterial infection." (PMID 27355424, 2016).
inflammation (7 papers, 2013 to 2022). Aberrant reaction of the microcirculation characterized by movement of fluid and leukocytes from the blood into extravascular tissues. "However, though endoparasites are more likely to be associated with eosinophilic or mixed inflammation, whether S100A12 expression in eosinophils is also induced or up-regulated in the context of inflammation in dogs has not been investigated." (PMID 29665827, 2018). "US is a sensitive modality for detection of synovitis, and thus the present findings indicate that the neutrophil protein S100A12 is a biomarker of synovial inflammation in RA." (PMID 25282581, 2014). "S100A8, S100A9, and S100A12 were supposed to directly stimulate the production of mucin 5AC (MUC5AC), a major mucin protein in the airway which closely correlated with airway inflammation." (PMID 35348596, 2022). "Understanding the role of S100A12 and MPO in the pathogenesis of chronic intestinal inflammation in future may result in an improved understanding of canine chronic intestinal inflammation." (PMID 26370713, 2015).
renal disease (3 papers, 2017 to 2021). "Urine S100A8/A9 and S100A12 levels were significantly higher (p<0.005 and p<0.05) in patients with active renal disease as compared with individuals with no or inactive renal disease." (PMID 32723832, 2020). "Patients who tested negative for anti-dsDNA antibodies and had active renal disease exhibited lower serum S100A12 levels when compared with those with no or inactive renal disease (p<0.05)." (PMID 32723832, 2020). "In this study, we determined serum and urine concentrations of S100 proteins S100A8/A9 and S100A12 in adult-onset SLE with or without active renal disease." (PMID 32723832, 2020). "Patients with normal serum complement and with active renal disease had lower serum S100A12 levels when compared with those with no or inactive renal disease (p<0.01)." (PMID 32723832, 2020). "Furthermore, patients with SLE with active renal disease had significantly higher urine/serum ratios of S100A8/A9 (p<0.05) and S100A12 as compared with individuals with no or inactive renal disease (p<0.005)." (PMID 32723832, 2020). "While serum S100A8/A9 levels were not different between patients with active renal disease compared with patients with SLE without or inactive renal disease, serum S100A12 protein levels were lower (p<0.005) in individuals with active renal disease." (PMID 32723832, 2020). "Conversely, S100 levels in the serum did not correlate with extrarenal or renal disease activity in cSLE, although serum S100A8/9 and S100A12 levels were higher in patients with active SLE than in healthy control subjects." (PMID 29065913, 2017).
respiratory disease (2 papers, 2012 to 2015). "More studies examining the serum values of S100A12 in respiratory disorders are required before a conclusion can be made about the value of serum S100A12 in these disorders." (PMID 22811950, 2012).
bone disorder (1 paper, 2017). "Alongside comparable plasma levels of bone disorder biomarkers—including serum calcium and phosphate, 25-OH vitamin D, 1,25-OH vitamin D, PTH, and FGF23—the average values of S100A12/ENRAGE, pentosidine, RAGE, and myeloperoxidase at baseline were very similar in the two study arms." (PMID 29362665, 2017).
gastrointestinal disorders (1 paper, 2020). "We conducted a scoping review of the existing literature to define what is known about the association of S100A12 with digestive disease and health." (PMID 32184815, 2020). "Together, these results reveal S100A12 is an important molecule broadly associated with the pathogenesis of digestive diseases." (PMID 32184815, 2020). "Together, these results reveal S100A12 is an important molecule broadly associated with the pathogenesis of digestive diseases and that S100A12 could be a potential biomarker for early diagnosis or a target for chemotherapeutic intervention." (PMID 32184815, 2020).
inflammatory myopathies (1 paper, 2023). "S100A12, a member of the S100 protein family, has unique proinflammatory activity and is significantly expressed in a variety of inflammatory myopathies." (PMID 37152368, 2023).
neurodegenerative disease (1 paper, 2025). A disorder of the central nervous system characterized by gradual and progressive loss of neural tissue and neurologic function. "After four hours of treatment, most KEGG pathways related to neurodegenerative diseases were upregulated in S100A12, but not in AGE-HS-treated cells." (PMID 40929163, 2025).
urinary tract diseases (1 paper, 2023). "However, tissue S100A12+ cell counts were significantly higher in both disease groups compared to healthy controls, resulting in significantly lower Cal-ratios in dogs with UC or non-neoplastic urinary tract diseases (NNUTD) compared to normal lower urinary tract tissues." (PMID 37946179, 2023).